IGF1 (insulin like growth factor 1)
Diseases named in the same sentence as IGF1 in open-access papers (continued):
Sharing a sentence is not in itself a finding about the gene and the disease.
cardiac hypertrophy (117 papers, 2008 to 2026). "The pathophysiological mechanisms underlying these observations likely involve IGF-1's role in promoting cardiac hypertrophy and fibrosis." (PMID 39544311, 2024). "In particular, the upregulation of IGF-1 has been implicated in the adaptive cardiac hypertrophy induced by mechanical loading, while potentially differential actions of IGF-1 isoforms in the myocardial repair/remodelling process have been proposed." (PMID 35159283, 2022). "Previous studies have shown that physiological cardiac hypertrophy is associated with an exercise-induced increase in the levels of IGF-1." (PMID 32140172, 2020). "These pathways are activated by extracellular growth factors such as insulin-like growth factor 1 (IGF-1) that has been linked to cardiac disease especially heart failure as it influences cardiac hypertrophy and contractile function." (PMID 31547508, 2019). "Insulin/IGF1 and HIF1α are the components of key signaling mechanisms that regulate ROS levels associated with aging and cardiac hypertrophy and failure." (PMID 31511561, 2019). "In the mouse model, an IGF-1 deficiency protects against abdominal aortic constriction-induced cardiac hypertrophy by dampening Akt signaling and glucose transporter 4 (GLUT4) levels." (PMID 30174600, 2018). "Overexpression of either IGF receptor or IGF-1 activates PI3K (p110α) will result in physiological cardiac hypertrophy and even MI, while a PI3K (p110γ) deficiency prevents HF induced by isoproterenol." (PMID 30174600, 2018). "The activation of insulin-like growth factor-1 (IGF-1)/phosphoinositide 3-kinase (PI3K)/Akt pathway has been implicated in adaptive cardiac hypertrophy with endurance exercise." (PMID 28509980, 2015). "The molecular mechanisms underlying cardiac hypertrophy and heart failure have been extensively studied, and many pathways involved in these processes have been uncovered, such as thyroid hormone, IGF1/Akt, calcineurin/NFAT and TGF-β/Smad-signaling pathways." (PMID 22926414, 2012). "The reduced insulin-like growth factor-1 (IGF-1) level in insulin-resistant patients has been reported to be associated with the higher circulating levels of the growth hormone and insulin resulting in cardiac hypertrophy." (PMID 33459867, 2021). "During hypertrophic stress, increased C/EBPβ downregulates the mir15a/mir16‐1 cluster, resulting in up‐regulation of multiple target proteins (INSR, IGF1R, AKT3, SGK1) in cardiomyocytes, causing increased activation of insulin/IGF1 signaling, ultimately causing cardiac hypertrophy and dysfunction." (PMID 33377640, 2020). "IGF1 signaling is also implicated in exercise-induced muscle and cardiac hypertrophy." (PMID 32587527, 2020). "Thus, IGF‐1 functions to prevent myocyte loss and to increase the size of cells 33, contributing to cardiac hypertrophy both in normal cardiac growth and in disease states." (PMID 29511611, 2018). "Furthermore, IGF‐1 deficiency alleviates cardiac hypertrophy in a model of abdominal aortic constriction." (PMID 29511611, 2018). "Insulin-related pathways (cluster I) are also associated with the susceptibility to cause physiologic cardiac hypertrophy by over-expression of insulin-like growth factor 1 (IGF-1) and insulin-like growth factor 1 receptor (IGF1R), via the PI3K (p110alpha) pathway." (PMID 24751578, 2014). "Besides, multiple hypertrophic stimuli, including pressure overload, β-adrenergic stimulation, angiotensin II and IGF-1, could cause mTORC1 hyperphosphorylation, and lead to exaggerated pathological cardiac hypertrophy." (PMID 34867324, 2021). "In the initial stages, it presents with cardiac hypertrophy and increased contractility and systolic output, features that can be reversed by adequate treatment to normalize GH and IGF-1 levels." (PMID 40142714, 2025).
cardiac hypertrophy (continued). "For instance, miR-1, whose expression is decreased by exercise, inhibits major regulators of cardiac hypertrophy, including calmodulin and insulin-like growth factor 1 (IGF-1), to suppress maladaptive growth." (PMID 40822014, 2025). "Angiotensin II (Ang II), endothelin-1 (ET-1), and insulin-like growth factor-1 (IGF-1) are some of the known neurohumoral factors that can induce cardiac hypertrophy via receptor tyrosine kinases or G-protein-coupled receptors such as Gαq." (PMID 38612393, 2024). "GH/IGF-1 leads to biventricular concentric cardiac hypertrophy, mainly left ventricular hypertrophy, including initially diastolic and then systolic heart dysfunction." (PMID 39598257, 2024). "Persistently increased secretion of GH and IGF-1 can result in liver hypertrophy, which is a form of visceral hypertrophy, and can disrupt glucose and lipid metabolism, leading to multiple comorbidities." (PMID 38370349, 2024). "Insulin-like growth factor-1 (IGF-1) can induce myocardial hypertrophy independently of insulin, and insulin can stimulate cardiomyocyte growth by interacting with IGF-1 receptors due to its structural similarity to IGF-1." (PMID 38540997, 2024). "One proposed mechanism is insulin resistance,where induction of myocardial hypertrophy is related to the structural similarityof insulin to IGF-1 and its ability to stimulate IGF-1 receptors." (PMID 39076279, 2023). "Physiological cardiac hypertrophy can develop in response to physiological stimuli such as exercise and pregnancy, and entails beneficial cardiac growth often mediated by the IGF1-Akt-C/EBPβ-CITED4 pathway." (PMID 37914850, 2023). "IGF1 is a key hormone that regulates the growth of cardiomyocytes and physiological cardiac hypertrophy." (PMID 37426419, 2023). "IGF-1/PI3K/Akt signaling pathway is a key mediator in regulating adaptive exercise-induced cardiac hypertrophy, thus inheriting the pivotal role of preserving ventricular myocyte function." (PMID 37655217, 2023). "In fact, an early study in mice shows that local overexpression of Igf1 does result in physiological cardiac hypertrophy in early life; however, this progresses to pathological hypertrophy accompanied by decreased contractile function at later time points." (PMID 37541969, 2023). "Insulin-like growth factor-1 (IGF-1) and the activation of its receptor have been implicated in phosphoinositide 3-kinase (PI3K)/Akt signaling, cardiomyocyte survival, and cardiac hypertrophy." (PMID 37627244, 2023). "Here, we examined previously reported factors and signaling pathways known to be involved in exercise-induced cardiac hypertrophy, including IGF1/PI3K/Akt signaling, C/EBPβ, miR-222, Cited4, and lncRNA CPhar4,5,7,41,42." (PMID 36351918, 2022). "Adrenergic activation, catecholamines, angiontensin II (AngII), endothelin 1 (ET-1), and insulin-like growth factor-1 (IGF-1) are well-known neurohumoral factors related to the development of cardiac hypertrophy." (PMID 35721030, 2022). "The IGF1/PI3K/AKT signaling pathway has been well described for its essential role in mediating exercise-induced physiological cardiac hypertrophy and myocardial protection." (PMID 36050310, 2022). "For example, overexpression of human IGF1 in skeletal and cardiac muscle of the mouse results in cardiac hypertrophy, which transitions to contractile dysfunction with age." (PMID 35250583, 2022). "IGF-1 participates in the initiation and development of physiological cardiac hypertrophy, and its cardiomyocyte-specific overexpression leads to cardiac hypertrophy in transgenic mice." (PMID 34407099, 2021). "A previous report showed that miR-322-5p was involved in cardiac hypertrophy in rats with pulmonary hypertension by targeting IGF-1." (PMID 34777504, 2021). "Lastly, the insulin-like growth factor-1 (IGF-1) and its receptor are also both targets of miR-1 and IGF-1 levels correlated with the extent of cardiac hypertrophy." (PMID 33946230, 2021).
cardiac hypertrophy (continued). "Insulin-like growth factor 1 and exercise can lead to AKT phosphorylation and eventually cause physiological adaptive cardiac hypertrophy." (PMID 34540911, 2021). "Acromegalic patients exhibit myocardial hypertrophy and interstitial fibrosis depending on the duration of growth hormone and IGF-1 excess." (PMID 34244467, 2021). "Growth hormone and insulin-like growth factor-1 can induce cardiac hypertrophy in vitro and in animal experiments, yet its concentration in humans is not high enough to cause cardiac hypertrophy." (PMID 32003781, 2020). "Pathway analysis prediction and reported target validation experiments revealed that the majority of exercise-regulated exomiRs are targeting genes that are related to IGF-1 signaling, a pathway involved in exercise-induced muscle and cardiac hypertrophy." (PMID 32587527, 2020). "The cPLA2 knockout mouse were previously identified to have cardiac fiber hypertrophy via modulating IGF-1 pathway signaling." (PMID 32811851, 2020). "mir15a/mir16‐1 protects against pathological cardiac hypertrophy and sequelae (e.g. heart failure) by repressing insulin/IGF1 signaling." (PMID 33377640, 2020). "We combine in vivo and in vitro studies to demonstrate that miR15a/mir16‐1 represses insulin/IGF1 signaling, preventing cardiac hypertrophy and dysfunction development." (PMID 33377640, 2020). "We demonstrate CM‐specific mir15a/mir16‐1 exhibits a protective role against the development of cardiac hypertrophy and dysfunction by suppressing insulin‐IGF1 signaling." (PMID 33377640, 2020). "Earlier studies have revealed that IGF-1/HIF1α pathway is activated during iron overload and ROS burst, in cardiac hypertrophy and aging conditions." (PMID 31511561, 2019). "This has been further demonstrated in rodents with heart failure where insulin-like growth factor-1 enhances ventricular hypertrophy and function and suppresses apoptosis of cardiomyocytes." (PMID 31547508, 2019). "Insulin-like growth factor-1 (IGF-1) was also reported to be among miR-1 cardiac targets mediating cardiac hypertrophy." (PMID 31547607, 2019). "Signaling cascades responsible for mediating physiological cardiac hypertrophy is IGF1-phosphoinositide 3-kinase (PI3KCA/p110α)-Akt-mTOR pathway." (PMID 31198561, 2019). "The signaling pathway by IGF-1 has been shown to have a key role in physiological cardiac hypertrophy because of its ability to regulate several cellular processes in the heart including growth, metabolism, and apoptosis." (PMID 31663002, 2019). "Since ADAR2 downregulation was associated with DCM we selected two cardiac hypertrophy and fibrosis associated genes (COL1A2 and IGF1) that are potential targets of miR-29b." (PMID 31039163, 2019). "Particularly in the heart, in addition to the cellular signaling pathway responsible for inducing physiological cardiac hypertrophy, IGF-1 also promotes formation of cardiomyocytes and protects against cell death." (PMID 31663002, 2019). "Insulin-like growth factor-1 (IGF-1), a crucial growth factor required for the proliferation, differentiation and survival of cardiomyocytes, mediates physiological cardiac hypertrophy through a PI3K-dependent pathway." (PMID 30174600, 2018). "The module also includes the genes IGF1 and IGF2 that are involved in the differentiation of immature cardiomyocytes and have been associated with cardiac hypertrophy." (PMID 30405693, 2018). "Our data suggest that reduced miR‐322‐5p contributes to the cardiac hypertrophy that occurs in PAH at least in part by increasing the expression of IGF‐1." (PMID 29511611, 2018). "Our data add to this study by indicating that IGF‐1 is an additional target of the miRNA, suggesting that reduced expression of this miRNA will help to promote cardiac hypertrophy by increasing the level of both IGF‐1 and its receptor." (PMID 29511611, 2018).
cardiac hypertrophy (continued). "The authors also confirmed the interaction of miR-1 and the IGF-1 gene in cell culture and in cardiac muscle cells of animals subjected to cardiac hypertrophy, where inverse expression between miR-1 and its target, IGF-1, was observed." (PMID 28505179, 2017). "GSK-3β has been described as a negative regulator of cardiac hypertrophy induced by endothelin-1, insulin-like growth factor 1, β-adrenergic agonists, and pressure overload." (PMID 27977752, 2016). "Various factors such as IGF-1, angiotensin II, endothelin, lead to the development of cardiac hypertrophy and that this requires a fully functional IGF-1 receptor." (PMID 24965872, 2014). "IGF-1/PI3K/Akt signaling molecules are reported to be critical for exercise-induced cardiac hypertrophy, in concert with AMP-activated kinase." (PMID 22761619, 2012). "Circulating IGF-1 and SirT1 have both been implicatedin the protection against cardiac hypertrophy,although the role of IGF-1 and/or its isoforms in this process remainscontroversial." (PMID 20228935, 2009). "There is compelling evidence that IGF-1 is involved in the intricate cascade of events leading to cardiac hypertrophy." (PMID 20676279, 2009). "Specifically IGF-1 promotes cardiac hypertrophy and increases muscle specific gene transcription (namely, troponin I, myosin light chain-2, and α-actin)." (PMID 20676279, 2009). "Furthermore, IGF-1 protein and the IGF-1 receptor are targets of miR-1, with their expression being inversely correlated with IGF-1 protein levels in models of cardiac hypertrophy." (PMID 40508033, 2025). "In fact, cardiac hypertrophy is a complex process, partly still unknown, governed by miR-1, -133a, and -208, and by insulin-like growth factor 1 (IGF-1)." (PMID 39768484, 2024). "The cross-talk between insulin and IGF1 signaling also contributes to physiological cardiac hypertrophy, with defects in IGF1 signaling exacerbating exercise-induced hypertrophy, as evidenced by studies on mice with cardiomyocyte-specific deletions of IGF1R and IRS." (PMID 39125938, 2024). "IGF1 is closely related to cardiac hypertrophy and heart failure." (PMID 37426419, 2023). "Similarly, increased level of Klotho and inhibition of insulin/IGF1/AKT axis was related to abolished myocardial hypertrophy and fibrosis in mice." (PMID 37985893, 2023). "Experimental studies have shown that excessive secretion of GH is related to glomerular sclerosis, and elevated IGF-1 levels may be involved in the occurrence of glomerular hypertrophy." (PMID 33521005, 2021). "IGF-1 participates in the physiological cardiac hypertrophy evoked by physical exercise." (PMID 34407099, 2021). "Interestingly, reoccurrence of mild cardiac hypertrophy was observed during IGF-1 treatment in one patient with lipodystrophy." (PMID 31840185, 2020). "In the heart, exercise-induced cardiac hypertrophy is dependent on IGF-1 signaling." (PMID 32587527, 2020). "Recently, Acta1 has been associated with cardiac hypertrophy through increased levels of IGF‐1, so the reduced levels of Acta1 in NLRP3−/− mice could be associated with the reduced serum levels of IGF‐1 shown in this study." (PMID 31625260, 2020). "Two genes Col1A2 and IGF1 were selected based on their role in cardiac fibrosis and hypertrophy." (PMID 31039163, 2019). "The overexpression of IGF-1 Ea can promote myofiber proliferation or heart hypertrophy." (PMID 29470680, 2018). "As its name suggests, IGF-1 promotes growth and may contribute to the development of both physiological and pathological cardiac hypertrophy." (PMID 29232706, 2017). "LRG1 overexpression might be able to reverse cardiac hypertrophy induced by the activation of IGF1/PI3K/Akt1 pathway, exercise, pressure overload, and in α-TM E180G transgenic mice." (PMID 28509980, 2015). "Understanding the role of LRG1 in TGFβ1 and IGF1 interactions may shed new light on the molecular mechanism of cardiac hypertrophy." (PMID 28509980, 2015).
cardiac hypertrophy (continued). "Signature cardiac hypertrophy pathways, such as IGF-1-, PI3K/Akt-, JAK/STAT-, and TH-signaling pathways, are mostly associated with physiological hypertrophy, whereas GPCR-, Ca2+-, ERK/MAPK-, and NFAT signaling pathways are associated with pathological hypertrophy." (PMID 25368602, 2014). "IGF1 signalling is an established factor in cardiac hypertrophy." (PMID 23879873, 2013). "IGF-1 contributes to cardiac hypertrophy via activation of PI3K/Akt signaling." (PMID 22761619, 2012). "Additionally, stretching cardiac fibroblasts was observed to induce low levels of IL-1β secretion; although these levels were insufficient to induce IL-6 production, these were enough to stimulate insulin-like growth factor-1 (IGF-1) for the induction of cardiac hypertrophy." (PMID 38256155, 2024). "Thus, MYH11 rare variants may trigger excessive SMC IGF-1 production and be the source of SMC-to-cardiomyocyte signaling to drive cardiac hypertrophy and failure in Myh11E1892D/E1892D mice after TAC." (PMID 39185210, 2024). "GH and IGF-1 may also stimulate some pathways, such as the phosphatidylinositol 3-kinase (PI3K/AKT) pathway and/or the mitogen-activated protein kinase (MAPK) pathway, associated with cardiac hypertrophy." (PMID 39598257, 2024). "IGF/IGF‐1 and twinfilin actin‐binding protein 1 (TWF1) are inhibited by miR‐1, which reduces cardiac hypertrophy and cardiac fibrosis." (PMID 39502130, 2024). "Considering the role of IGF1 in cardiac disorders, the ability of Klotho to inhibit IGF in several heart hypertrophy models was investigated." (PMID 37985893, 2023). "It is unclear to what extent the differences in left heart impairment between the sexes could also be influenced by the differences in elevated IGF-1 levels, which could lead to increased LVM, suggesting its role in cardiac hypertrophy in APs." (PMID 40429391, 2025). "Class IA PI3K(p110α), the cardiac-protective isoform of PI3K, acts as a master effector of insulin-like growth factor 1 (IGF-1), upstream activator of PI3K in the heart, which is known to be responsible for exercise induced myocardial hypertrophy and even for an increased cardiac contractility." (PMID 37655217, 2023). "However, the larger share of pathways (5 of 10) were related to growth: cardiac hypertrophy, Wnt/β‐catenin, PI3K/AKT, IGF‐1 and PTEN." (PMID 35293040, 2022). "As anabolic hormones, insulin and IGF1 promote cardiac growth, playing a major role in coupling nutritional status to cell size rather than necessarily contributing to cardiac hypertrophy." (PMID 35766350, 2022). "Phosphorylation of GSK3α/β in response to insulin or IGF1 in the heart and cardiomyocytes is well-documented, although the emphasis is generally on its role in cardiac hypertrophy, rather than regulation of glycogen synthesis." (PMID 35766350, 2022). "In addition, a previous study has reported that exercise affects growth hormone and insulin-like growth factor-1 (IGF-1) and PI3K/AKT pathways, resulting in cardiac hypertrophy and protection." (PMID 35781843, 2022). "Finally, several genes whose increased expression has been shown to lead to cardiac hypertrophy and heart diseases are also upregulated in WRF rat heart, including Insulin-like growth factor 1 (Igf1), Angiotensin (Agt), and Cathepsin K (Ctsk)." (PMID 35236346, 2022). "Although AngII infusion induced a similar degree of cardiac hypertrophy, fractional shortening, which increased in mice treated with AngII/vehicle, was not increased in AngII/IGF-1-infused mice compared with that in AngII/vehicle-infused mice." (PMID 34244467, 2021). "Changes in miR‐322‐5p are not the only ones that occur in cardiac hypertrophy that are likely to affect the IGF‐1 signalling system." (PMID 29511611, 2018).